GPX2 (glutathione peroxidase 2)
Diseases named in the same sentence as GPX2 in open-access papers (continued):
Sharing a sentence is not in itself a finding about the gene and the disease.
prostate carcinoma (17 papers, 2015 to 2024). A carcinoma that arises from epithelial cells of the prostate gland. "It has also been shown that GPX2 overexpression contributes to the initiation, development, and spread of lung, hepatocellular, colon, and prostate cancers." (PMID 39125992, 2024). "GPX3 was downregulated in breast, colorectal, lung, and prostate cancers, with GPX2 showing a similar pattern in all but colorectal and prostate cancers." (PMID 39594421, 2024). "For instance, GPX2 was overexpressed in colon and lung cancers but downregulated in breast and prostate cancers." (PMID 39594421, 2024). "MiR-17-3p elevated ROS levels by inhibiting three primary mitochondrial antioxidants, MnSOD, glutathione peroxidase 2 (Gpx2) and thioredoxin reductase 2 (TrxR2), remarkably strengthening the sensitivity of prostate cancer cells to IR." (PMID 35081965, 2022). "MiR-17-3p has been revealed to target antioxidant enzymes, including GPx2, thus enhancing radiosensitivity in prostate cancer." (PMID 35892591, 2022). "For example, GPX1, SELENOF, and SELENOP levels were significantly reduced in prostate cancer models, whereas GPX2 was significantly increased." (PMID 32933107, 2020). "In prostate cancer cells miR-17-3p targets MnSOD, GPX2, and TXNRD2 leading to ROS accumulation." (PMID 34199590, 2021). "More relevant to our work, it has been shown that miR-17-3p downregulates important anti-oxidant enzymes, such as manganese superoxide dismutase, glutathione peroxidase-2 and thioredoxin reductase-2 (TrxR2) in prostate cancer cell lines and blood mononuclear cells." (PMID 27505139, 2016). "The changes in activity of GPX1, GPX2, and GPX3 isoforms may be associated with the development of cancers, for example, prostate cancer or even colon cancer." (PMID 26682223, 2015). "Moreover, a previous study demonstrated that targeting mitochondrial antioxidants, including manganese superoxide dismutase (MnSOD), glutathione peroxidase 2 (Gpx2), and thioredoxin reductase 2 (TrxR2) by microRNA-17-3p remarkably sensitized prostate cancer cells to IR." (PMID 34249928, 2021). "In addition to SOD2, miR-17-3p also targets GPX2 in prostate cancer cells." (PMID 34199590, 2021). "Xu and colleagues reported miR-17-3p could repress three major mitochondrial antioxidant enzymes (manganese superoxide dismutase (Mn-SOD), glutathione peroxidase 2 (Gpx2), and thioredoxin reductase 2 (TrxR2)) and enhance the radiosensitivity of prostate cancer cells." (PMID 32411322, 2020). "GPX3 gene codes for the Glutathione peroxidase 3, also known as plasma glutathione peroxidase (GPx-P), the variations in activity of GPX1, GPX2, and GPX3 isoforms may be associated with the development of cancers, for example, prostate cancer or even colon cancer." (PMID 27874091, 2016). "Overall, these data are consistent with the significant correlation found between the combined gene expression of GPX2, EP300, and PSMB2, and OS in prostate cancer patients." (PMID 32933107, 2020). "Additionally, research investigating the mRNA profile of DU145 cells treated with sodium selenite observed an increased expression of GPX1, GPX2, and GPX4 and a decreased expression of TXNRDs in prostate cancer." (PMID 37765058, 2023). "GPX2, a key molecule of the glutathione redox system that acts in concert to provide a coordinated network of protection against ROS accumulation and oxidative damage, has been suggested as a prognostic marker in CRPC, and its silencing is able to inhibit prostate cancer growth." (PMID 32933107, 2020).
colorectal cancer (14 papers, 2013 to 2024). A primary or metastatic malignant neoplasm that affects the colon or rectum. "SELENOH downregulated colorectal cancer cells showed increased growth properties, and loss of GPX2 and SELENOF impaired growth of colorectal cancer cells." (PMID 35433131, 2022). "Colon/rectum and colorectal cancer (CRC) are cases where GPX2 levels are high enough to have an impact on ROOH levels." (PMID 39329876, 2024). "Colorectal cancer (CRC) was selected as a case study for examining GPX2 function, as colorectal tissues and cancers are sites where GPX2 is highly expressed." (PMID 39329876, 2024). "Similar to GPx1, unusual expression of GPx2 is also observed in different tumors; for example, GPx2 is overexpressed in colorectal cancer, whereas a lower expression of GPx2 is detected in prostate intraepithelial neoplasia." (PMID 38202704, 2023). "Antioxidant activities and protection against colorectal cancer (promoted the gene expression of GPx-1 and GPx-2 and enzyme activity of GPx-1 in rat colon)." (PMID 38202719, 2023). "The probability of relapse-free survival in colorectal cancer patients was lower in the case of high expression of GPX2 in the tumor." (PMID 35433131, 2022). "Redox signaling in colorectal/intestinal cancer progression is complex, as studies have found that endogenous antioxidants (NRF2 and GPX2) can support colorectal cancer progression." (PMID 33557356, 2021). "GPx2, a gastrointestinal tract GPx isoform, overexpression was observed in gastric cancer (both primary and metastatic foci) and colorectal cancer tissue when compared with normal tissue." (PMID 34381561, 2021). "A high expression of GPX2 was related with the cell death resistance observed in HT-29 colorectal carcinoma cell line." (PMID 33540681, 2021). "In contrast, while GPX2 expression between pancreatic and colorectal carcinoma biopsies was very similar in our experiments, UALCAN data indicate higher variability among pancreatic carcinoma patients." (PMID 33540681, 2021). "The abnormal expression of GPx2 was detected in different tumors, and GPx2 was up-regulated in colorectal cancer and down-regulated in prostate intraepithelial neoplasia, suggesting that GPx2 plays complex roles in tumorigenesis." (PMID 32571353, 2020). "The level of GPX2 was increased in lung adenocarcinoma and colorectal cancer." (PMID 35712475, 2022). "In the analysis performed in UALCAN, the highest GPX2 expression occurred in colorectal carcinoma patients, followed by pancreatic carcinoma patients, in which GPX2 expression is approximately 85% with respect to the expression observed in colorectal carcinoma." (PMID 33540681, 2021). "Overexpression of GPx2 was observed in several tumors including colorectal cancer, Barrett’s esophagus carcinoma, and lung cancer, indicating that GPx2 may be an oncogene." (PMID 29108391, 2017). "Therefore, we analyzed the effect of GPx2 in a mouse model mimicking sporadic colorectal cancer (azoxymethane-treatment only)." (PMID 23977205, 2013). "In addition, GPX2 is overexpressed in 11% and 60% of biopsies with pancreatic and colorectal carcinoma, respectively, while it is not expressed in glioblastoma." (PMID 33540681, 2021).
lung carcinoma (11 papers, 2017 to 2025). "Co-expression analysis in lung cancer tissues also confirmed that GPX2 was positively correlated with Hedgehog signaling and cancer stem cell markers while negatively correlated with METTL14." (PMID 40533443, 2025). "To assess the clinical relevance of GPX2 expression in gefitinib response, we collected tumor tissues from lung cancer patients undergoing TKI therapy." (PMID 40533443, 2025). "Survival data from male patients with lung cancer showed that mutations in GCLC, and GPX2, key genes in glutathione metabolism, contribute to a bad prognosis." (PMID 32850411, 2020). "High expression of GPX2 in lung cancer promotes ferroptosis." (PMID 40428318, 2025). "GPX2 has been studied in lung cancer, with reports indicating its involvement in apoptosis, immune regulation and oxidative stress, with clinical significance in lung cancer." (PMID 40971773, 2025). "Similarly, gene expressional analysis in lung cancer from TCGA database revealed a positive correlation between GPX2 and CD133, as well as ALDH1A1." (PMID 40533443, 2025). "The activation of Nrf2 and its downstream enzyme GPX2 may promote radioresistance or cisplatin resistance in HNC or lung cancer." (PMID 38132173, 2023). "Notably, the percentage of Ki-67 positive area in GPX2-high expression group is also larger than GPX2-low expression group, implying that low GPX2 level in lung cancer may serve as an evaluating indicator for TKI response." (PMID 40533443, 2025). "Nevertheless, GPX2 and GPX3 are engaged in the body’s metabolic mechanism for maintaining glutathione levels, which can successfully prevent lung cancer." (PMID 37955007, 2023). "Immunohistochemical (IHC) staining revealed that TKI-nonresponse specimens from patients with lung cancer exhibited more intense IHC staining of GPX2 compared to TKI-response group." (PMID 40533443, 2025). "Additionally, the high expression of GPX2 and the low expression of ANPEP, and GPX3 also reduced the survival time of men with lung cancer." (PMID 32850411, 2020).
hepatocellular carcinoma (9 papers, 2020 to 2026). A malignant tumor that arises from hepatocytes. "The protein Gpx-2 plays a vital role in inducing apoptosis in hepatocellular carcinoma cells (HCC cells) through lenvatinib therapy and serves as a biomarker for guiding treatment in HCC patients." (PMID 37834097, 2023). "Additionally, GPX2 contributes to lenvatinib resistance in hepatocellular carcinoma (HCC) through its influence on oxidative stress and energy metabolism." (PMID 41145471, 2025). "Glutathione peroxidase 2 (GPX2), a member of the antioxidant enzyme GPX family, overexpression can induce poor prognosis of hepatocellular carcinoma patients." (PMID 35705729, 2022). "In fact, the knockdown of p65 by siRNA enhanced the NRF2-mediated activation of HO-1, GPX2, and NQO1 genes in hepatoma HepG2 cells, whereas co-transfection of HO-1(ARE), GPX2(ARE), or NQO1(ARE)-Luc reporters with either NF-κB, p65, or IKKβ expressing vectors inhibited ARE-driven expression." (PMID 38539832, 2024). "NRF2 SUMOylation promotes the elimination of ROS in cells by increasing the transcription of glutathione peroxidase 2 (Gpx2), which leads to the upregulation of PHGDH in hepatocellular carcinoma (HCC) cells." (PMID 37147729, 2023).
colon cancer (7 papers, 2013 to 2024). "In colon cancer, high GPX2 expression has been associated with early tumor recurrence, and H2O2 neutralization by GPX2 has been identified as essential for maintaining clonogenic and metastatic capacity." (PMID 33282950, 2020). "Thus, the anti-carcinogenic activity of GPx2 in inflammation-triggered colon cancer is mainly caused by its anti-inflammatory role." (PMID 23977205, 2013). "Decreased GPx2 expression was detected in colon cancer, pancreatic cancer, cancers of the bladder and urinary tract, and esophageal colon carcinomas, whereas increased GPx2 expression was detected in several carcinomas." (PMID 39404411, 2024). "Investigated end points included proliferation, ROS induction, and expression of cell cycle-, apoptosis- and antioxidant-relevant proteins (Cyclin D2, p21, PARP, Bid, GPx2) in colon cancer cells." (PMID 36672389, 2023). "Therefore, a downregulation of GPx2 may be associated with a lower risk for colon cancer promotion." (PMID 36672389, 2023). "It was also reported that cells with GPX2 knock-down had a higher capability to invade and migrate than the GPX2-expressing controls in colon cancer." (PMID 29662611, 2018). "Overexpression of the GPX2 gene is observed in many diseases, mainly in cancers, such as colon cancer, squamous cell carcinoma, and pulmonary adenocarcinoma, as well as in premalignant lesions like Barrett's esophagus." (PMID 26682223, 2015). "According to the colon cancer Cox regression test and Kaplan–Meier (K-M) curves of key genetic risk factors, the five most significant genes selected were: ELAV-like RNA-binding protein 1 (ELAVL1), GPX2, EPAS1, SLC7A5, and high mobility group box 1 (HMGB1)." (PMID 36324584, 2022). "However, studies indicated that GPx2 may have a divergent role in colon carcinogenesis since it is overexpressed in colon cancer cells and might protect the cancer cells from ROS-induced cell death." (PMID 36672389, 2023). "We identified five core genes, ELAVL1, GPX2, EPAS1, SLC7A5, and HMGB1, involved in the ferroptosis of colon cancer." (PMID 36324584, 2022). "Our results suggest that five core genes, ELAVL1, GPX2, EPAS1, SLC7A5, and HMGB1, are involved in the ferroptosis of colon cancer cells." (PMID 36324584, 2022).
glioblastoma (7 papers, 2004 to 2025). The most malignant astrocytic tumor (WHO grade IV). "In fact, the role of GPx-2 in forming a multigene prognosis model for glioblastoma multiforme has been suggested, where a significant association of higher gpx2 expression with poorer prognosis was detected." (PMID 37761814, 2023). "In one instance, GPX2 was shown to be detected in glioblastoma multiform (GBM) by IHC from The Human Protein Atlas (THPA), a cancer that barely expresses GPX2." (PMID 39329876, 2024). "A retinoic acid response element (RARE) has been identified in the promoter region of a specific isoform of glutathione S-transferase-pi (GSTp) in glioblastoma cells and GPX2, an enzyme necessary for the conversion and utilization of GSH." (PMID 15613237, 2004). "Furthermore, Kaplan–Meier analysis suggests that a high GPX2 expression in glioblastoma patients results in a low survival rate (p-value: 0.0035)." (PMID 33540681, 2021). "Low or no expression of GPX2 observed in glioblastoma cell lines and biopsies is in accordance with data collected in UALCAN." (PMID 33540681, 2021). "In contrast, no GPX2 expression was observed in any of the glioblastoma biopsies." (PMID 33540681, 2021).
lung adenocarcinoma (7 papers, 2021 to 2024). A carcinoma that arises from the lung and is characterized by the presence of malignant glandular epithelial cells. "The expression of GPX2 in lung adenocarcinoma and its effect on survival were analyzed by the TCGA database and the GEPIA 2 database." (PMID 35898928, 2022). "IHC showed that GPX2 was highly expressed in lung adenocarcinoma tissues and lowly expressed in paracancerous tissues." (PMID 35898928, 2022). "It is proved that GPX2 can promote the migration and invasion of lung adenocarcinoma cells and is related to the EMT/β-catenin pathway." (PMID 35898928, 2022). "The relationship between GPX2 gene expression and lung adenocarcinoma was analyzed by the GEPIA database." (PMID 35898928, 2022). "The positive expression rates of GPX2 in lung adenocarcinoma and its paracancerous tissues were 66.0% and 15.7%, respectively (P < 0.05)." (PMID 35898928, 2022). "Bioinformatics analysis showed that the expression of GPX2 was strongly correlated with the prognosis of lung adenocarcinoma patients (P < 0.01)." (PMID 35898928, 2022). "Numerous studies have confirmed that the expression of GPX2 is significantly upregulated in gastrointestinal tumors, liver tumors, glioblastoma, lung adenocarcinoma, breast cancer, and other cells." (PMID 35898928, 2022). "A total of 45 cases of primary lung adenocarcinoma tissue specimens and 45 cases of their paracancerous tissue specimens were collected, and the expression of GPX2 in the two types of tissues was detected by immunohistochemistry." (PMID 35898928, 2022). "This shows that GPX2 plays an important role in the development and progression of lung adenocarcinoma, which is expected to provide a basis for clinical diagnosis and treatment of lung adenocarcinoma." (PMID 35898928, 2022). "In fact, it has been reported that silencing GPX2 partially reverses erastin-induced ferroptosis in lung adenocarcinoma, indicating a potential role of GPX2 as a ferroptosis driver in lung adenocarcinoma." (PMID 35992146, 2022). "Elevated GPX2 mediates the resistance of lung adenocarcinoma to cisplatin." (PMID 37743483, 2023). "The expression of GPX2 in lung adenocarcinoma is related to the prognosis of patients." (PMID 35898928, 2022). "The positive expression rates of GPX2 in lung adenocarcinoma tissues and paracancerous tissues were 60.0% and 15.5%, respectively, with statistically significant differences between groups P < 0.05.The comparison between groups was performed by the chi square test." (PMID 35898928, 2022). "Thus, GPX2 is expected to be an important target for the diagnosis and treatment of lung adenocarcinoma." (PMID 35898928, 2022). "This led us to further speculate that GPX2 may enhance the invasive ability of lung adenocarcinoma A549 cells by controlling the expression of MMP2 and MMP9 proteins in lung adenocarcinoma cells." (PMID 35898928, 2022). "The expression of NTS was highly correlated with that of CPS1, fibrinogen gamma (FGG), and glutathione peroxidase 2 (GPX2) in a subgroup of lung adenocarcinoma samples, suggesting these genes might belong to a gene coexpression network." (PMID 33493519, 2021). "In lung adenocarcinoma, lower RFS seems to be related to persister cells that maintain higher levels of GPX2 expression, which may be essential for the resilience of this cell type both in the quiescent and cycling states." (PMID 39329876, 2024).
pancreatic cancer (7 papers, 2020 to 2024). "The downregulation of β-catenin, Vimentin and Snail and the upregulation of E-cadherin were observed as a result of Gpx-2 silencing in pancreatic cancer cells." (PMID 37834097, 2023). "GPX2 expression in pancreatic carcinoma cell lines was in the range 0.005–0.120% with respect to HT-29 expression." (PMID 33540681, 2021). "In addition, cluster 5/GPx2 KD up-regulated S100 genes, known to play a role in metastatic fitness of pancreatic tumors, and galectin genes, which may guide therapeutic resistance, and hence tumor recurrence or metastasis." (PMID 35193955, 2022). "The only exceptions were (i) GPX2, whose high expression levels correlated with OS in breast and head and neck cancers; and (ii) TXNRD1, whose high expression levels correlated with poor OS in head and neck, kidney, liver, and pancreas cancers." (PMID 32933107, 2020). "Specifically, GPX2 downregulation is contrasting because it has been reported as a regulator of EMT markers, enhancing invasion, and metastasis targeting the Wnt pathway in cervical and pancreatic cancer." (PMID 32850411, 2020).
gastric cancer (6 papers, 2021 to 2025). A primary or metastatic malignant neoplasm involving the stomach. "Survival analysis indicated that elevated GPX2 expression was closely associated with poor prognosis in gastric cancer patients." (PMID 41145471, 2025). "While our findings establish GPX2 as a promising therapeutic target for overcoming cisplatin resistance in gastric cancer, clinical translation faces significant challenges." (PMID 41145471, 2025). "Glutathione peroxidase 2 (GPx2) contributes to the progression and metastasis of gastric cancer by enhancing the KYNU-Kyn-AhR signaling pathway." (PMID 38462620, 2024). "The effect of GPx2 expression on the prognosis of gastric cancer is still controversial." (PMID 37138031, 2023). "In addition, we measured GPx2 and GPx1 expression in gastric cancer tissues and paired paracancerous tissues by Western blotting." (PMID 37138031, 2023). "Additionally, we performed GPX2 rescue experiments by reintroducing GPX2 via lentiviral overexpression in GPX2-knockdown gastric cancer cells, and the results demonstrated that GPX2 reconstitution significantly reversed the reduced lipid droplet formation induced by GPX2 knockdown." (PMID 41145471, 2025). "The results revealed that GPx2 expression impacted kynurenines (KYNU)-mediated metabolism, in addition to the involvement of the reactive oxygen species (ROS)-mediated KYNU-kyn-AhR signaling pathway in gastric cancer progression and metastasis following GPx2 knockdown." (PMID 39409942, 2024). "Moreover, ebselen increased the expression of GPX2 and GPX4 in SGNs after peroxynitrite injury, which is consistent with previous studies that ebselen can increase the expression of GPX2 or GPX4 in rat stomach, gastric cancer cells, or cochlea." (PMID 35401119, 2022).